IGLL3P (immunoglobulin lambda like polypeptide 3, pseudogene)
Synonyms: 16.1; formerly IGLL3
Gene: Transcribed unprocessed pseudogene on chromosome 22 (25,318,256 to 25,320,080, forward strand). Ensembl gene ENSG00000206066.
Diseases named in the same sentence as IGLL3P in open-access papers:
IGLL3P is named in the same sentence as 2 diseases in open-access papers, as found by Europe PMC text mining. Sharing a sentence is not in itself a finding about the gene and the disease. The quoted sentences say what the papers report.
breast carcinoma (1 paper, 2015). "Of them, a set of genes related to immune function, such as CXCL13, IGHM, IGLL3P, IGJ and IGKC, were up-regulated in young patients with breast cancer." (PMID 25990390, 2015).
IGLL3P also shares sentences with these, for which no sentence is quoted: tumor (1 paper).